AKT2 (AKT serine/threonine kinase 2)
Diseases named in the same sentence as AKT2 in open-access papers (continued):
Sharing a sentence is not in itself a finding about the gene and the disease.
breast cancer (continued). "Highly invasive breast cancer cells have been studied and selected, and these cells displayed EMT characteristics and dramatically enhanced invasive abilities with decreased levels of E-cadherin and increased vimentin, fibronectin, Twist and AKT2." (PMID 27453691, 2016). "Together, the data suggest that AKT2 is not causal for the metastatic lesion, but that CCND1 likely has a role in the primary breast cancer that is reinforced in the metastatic cancer." (PMID 25970776, 2015). "Furthermore, prolonged down-regulation of AKT2 using siRNA induces conversion of LC3-I to LC3-II, resulting in cell death by autophagy of the mitochondria in breast cancer cell line MDA-MB231." (PMID 24946858, 2014). "Disruption of Akt1 or Akt2 did not affect cell morphology or the expression of luminal or basal cytokeratins in mammary tumors." (PMID 23919516, 2013). "Despite the absence of Akt1 or Akt2, mammary tumors that developed in the MTB-IGFIR mice maintained detectable levels of phosphorylated Akt." (PMID 23919516, 2013). "Similarly, the levels of Akt2 were undetectable in MTB-IGFIR/Akt2−/− mice while Akt1 levels were similar in MTB-IGFIR mammary tumors and mammary tumors from MTB-IGFIR/Akt2−/− mice." (PMID 23919516, 2013). "It is also important to point out that necrosis was shown recently to be a typical representative of basal-like breast cancer, and that in breast cancer patients whose tumors overexpress HER2, higher levels of activated AKT2 and the hypoxic-induced protein; HIF-1α were observed." (PMID 22511931, 2012). "Therefore, we sought to explore the relationship between activation and compartmentalization of Akt1 and Akt2 and the outcome of targeted therapy in a sample of patients with metastatic HER2-positive breast cancer treated with trastuzumab." (PMID 22842582, 2012). "Another study in 402 ERα-positive breast cancer patients showed clearly that cytoplasmic Akt1 and Akt3, but not Akt2, expression was correlated significantly with pAkt expression." (PMID 18184439, 2008). "Akt2 could also be activated by another EMT-inducer, Twist, in invasive breast cancer cells." (PMID 38002001, 2023). "However, recent study demonstrated that both breast-specific Akt1 and Akt2 deletion impaired breast cancer development driven by ErbB2 overexpression, but breast cancer metastasis was not affected by breast-specific Akt1 deletion." (PMID 36180910, 2022). "Interestingly, these authors did not detect significant changes of SDMA on AKT2/3 in breast cancer upon PRMT5 inhibition, which is consistent with our observation." (PMID 35803962, 2022). "Based on next-generation sequencing analysis, genetic alteration in Akt1 (E17K and other pathologic mutations) was significantly enriched in metastatic breast cancer compared to primary breast cancer and Akt1, but not Akt2 or Akt3, was identified as an actionable target." (PMID 34298660, 2021). "In opposition to the studies confirming distinct roles of AKT1 and AKT2 in cell proliferation and tumor growth, Watson and Moorehead attribute AKT1 knockdown as well as AKT2 knockdown to a suppressing effect on tumor initiation and growth of an IGF1R-positive breast cancer mouse model." (PMID 31752925, 2019). "In PC-3 prostate cancer cells, siRNA-mediated knockdown of AKT1 inhibited cell migration and cell adhesion, whereas AKT2 knockdown promoted cell migration suggesting that AKT1 has a pro- and AKT2 has an antimigratory role in prostate cancer, in contrast with their functions in breast cancer." (PMID 28082369, 2017). "Additionally, we expanded our binding analysis to full-length Akt2 and Akt3 to investigate whether the other Akt isoforms interact in a comparable manner with DNA-PKcs in NSCLC as well as in breast cancer cells." (PMID 29090098, 2017).
breast cancer (continued). "In vitro studies in breast cancer cell lines suggest that AKT1-mediated degradation of the pro-invasion transcription factor NFAT and the tumour-suppressor tuberous sclerosis complex 2 (TSC2) decreases, whereas AKT2-mediated up-regulation of pro-invasive β1-integrin promotes cell migration." (PMID 28082369, 2017). "Interestingly, although WDR26 selectively regulates PI3Kβ and AKT2 signaling, its activity on breast cancer cell growth and migration does not seem to depend on the status of PI3Kα mutation, PTEN expression or RTK overexpression." (PMID 26895380, 2016). "Evaluation of Akt1, Akt2 and Akt3 revealed that Akt1 and Akt2 can be detected in both WT mammary tissue and mammary tumors while Akt3 could not be detected in either WT mammary tissue or mammary tumors." (PMID 23919516, 2013). "However, an increased tumor burden in Akt2 null mice is not consistently seen in mouse models of lung cancer or other tumors such as mammary tumors, which would be expected if hyperglycemia was the driving force behind accelerated tumorigenesis in Akt2−/− models." (PMID 26654940, 2016). "Akt1, but not Akt2, was shown to promote breast cancer cell proliferation by upregulating cyclin D1 and S6 (a downstream target of mTORC1) in IBH-6 and T47D breast cancer cells." (PMID 34298660, 2021). "Ablation of AKT1, but not of AKT2, also promotes EMT of breast cancer cells especially after TGF-β stimulation by decreasing the amounts of the miR-200 family." (PMID 31752925, 2019). "Whereas AKT2 does not display such a phenotype, AKT3 promotes angiogenesis via VEGF and c-Myc in breast cancer." (PMID 31752925, 2019). "Although, AKT1, AKT2 and AKT3 share a high homology, are activated and regulated by the same upstream mechanisms and share a wide range of substrates, the three isoforms exert non-redundant and partly opposing roles in breast cancer." (PMID 31752925, 2019). "However, there is growing evidence that the different isoforms AKT1, AKT2 and AKT3 have non-redundant and partly opposing effects in tumorigenesis, making pan-AKT inhibition in breast cancer inappropriate." (PMID 31752925, 2019). "Investigations of ER positive human breast cancer probes revealed AKT1 deletions in 4.8%, AKT1 amplifications in 1%, AKT2 deletions in 21.1%, interestingly no AKT2 amplifications, no deletions of AKT3, but AKT3 amplifications in 9.9% of investigated ER-positive human breast cancers." (PMID 31752925, 2019).
Insulin resistance (105 papers, 2010 to 2026). Increased resistance towards insulin, that is, diminished effectiveness of insulin in reducing blood glucose levels. "In humans, variants in AKT2 that lead to a deficient insulin signaling have also been associated with a major risk of insulin resistance and T2DM." (PMID 39201476, 2024). "AKT2 is the predominant isoform in human skeletal muscle and its inactivating missense mutation leads to severe insulin resistance and type 2 diabetes." (PMID 36409629, 2023). "It has been reported that Akt2 whole-body knockout mice display a severe type-II diabetes phenotype and that human patients with mutations in Akt2 show severe insulin resistance and develop diabetes." (PMID 37443129, 2023). "Finnish-specific gene variant p.P50T/AKT2 (minor allele frequency (MAF) = 1.1%) is associated with insulin resistance and increased predisposition to type 2 diabetes." (PMID 36409629, 2023). "One single family has been identified with partial lipodystrophy and severe insulin resistance that is due to a missense mutation in the AKT2 gene encoding the key insulin signalling ser/thr kinase." (PMID 35250856, 2022). "AKT2-deficient mice display severe systemic and muscle insulin resistance and progressive lipodystrophy affecting all WAT depots." (PMID 35250856, 2022). "In particular, it has been reported that Akt2 whole-body knockout mice display a severe type-II diabetes phenotype and that human patients with mutations in Akt2 show severe insulin resistance and develop diabetes." (PMID 36229454, 2022). "Mice with global Akt2 gene deletion (Akt2‐KO) or people having Akt2 mutation gene have classic insulin resistance and type 2 diabetes (T2D) phenotype." (PMID 34053181, 2021). "In support of this, a study showed decreased secretions of IRS 1 and Akt2 in obese conditions, the major predisposing factor to insulin resistance." (PMID 33953863, 2021). "The missense loss-of-function mutation AKT2-Arg274His leads to hyperinsulinemia and insulin resistance in humans, highlighting the importance of AKT2 in mediating insulin signalling." (PMID 33893069, 2021). "It was found that the loss of Akt2 in mice can cause insulin resistance, which leads to diabetes mellitus-like." (PMID 32325903, 2020). "In fact a dominant negative Akt2 mutation was identified in a family to associate with severe insulin resistance and diabetes suggesting its role in metabolic regulation." (PMID 30444896, 2018). "Of these isoforms, it is the disruption of Akt2 that is associated with impaired glucose uptake, insulin resistance and diabetes in humans and mice, indicating that Akt2 is particularly important in mediating metabolic insulin responses." (PMID 30524379, 2018). "A missense mutation in AKT2 that causes loss of AKT2 function leading to insulin resistance was identified in a family with diabetes." (PMID 29173281, 2017). "Inactivating mutations in Akt2 correlate with insulin resistance in humans and genetic deletion of Akt2 in mice causes an insulin resistance-like phenotype." (PMID 25856301, 2015). "Although genetic mutations in the coding region of Akt2 resulting in insulin resistance are rare, the loss-of-function mutation (R-H274) signifies the importance of Akt2 in intermediate glucose metabolism." (PMID 26465754, 2015). "Multiple studies have indicated that Akt2 is the primary isoform responsible for insulin-stimulated glucose uptake in humans as well as rodents and dysfunctional Akt2 is associated with insulin resistance and impaired glucose tolerance." (PMID 26465754, 2015). "The ultimate outcome of the loss of PI3K-C2γ, together with the reduction in prolonged Akt2 activation, was insulin resistance and adiposity." (PMID 26100075, 2015). "A mutation in the gene encoding the protein kinase AKT2/PKB-β reveals the autosomal dominant inheritance of severe insulin resistance and diabetes mellitus." (PMID 23579596, 2013).
Insulin resistance (continued). "Insulin resistance in human metabolic syndrome patients is associated with decreased expression of the insulin receptor substrate-2- (Irs2-) AKT2 axis in mononuclear leukocytes (MLs)." (PMID 22347652, 2011). "Among them, Pparg and Akt2 (targets of mir-30b), Hnf1b, Hnf4a, and Lmna (targets of mir-30d), are well-known genes implicated in T2D or insulin resistance." (PMID 21124896, 2010). "Mutation in AKT2 (R274H) enzyme has been shown to result in autosomal dominant inheritance of severe insulin resistance and T2D." (PMID 20122255, 2010). "In conclusion, myotubes from p.P50T/AKT2 variant carriers show multiple signalling alterations which may contribute to predisposition to insulin resistance and T2D in the carriers of this signalling variant." (PMID 36409629, 2023). "We next hypothesized that there might be a gene–environment interaction that accentuates insulin resistance in p.P50T/AKT2 variant carriers." (PMID 36409629, 2023). "Regarding AKT2, whereas there are so far no mouse model harbouring the R274H mutation described to lead to human partial lipodystrophy and severe insulin resistance, adipocyte-specific AKT2 deficiency recapitulates lipodystrophy associated with impaired glucose homoeostasis." (PMID 35250856, 2022). "Moreover, it is likely that this enzyme by affecting the structure and function of proteins such as insulin receptor substrate 1 (IRS1) and serine/threonine-protein kinase 2 (AKT2) as well as by reducing insulin signaling cause insulin resistance." (PMID 31231498, 2019). "Furthermore, knockdown or mutations of Akt2/PKBβ resulted into severe insulin resistance and altered glycemia, probably because defects of this important mediator lead to a reduction of AS160-induced GLUT4 translocation in both mice and humans." (PMID 30469501, 2018). "On the other hand, Akt2-deficient mice exhibit normal growth, but develop a diabetes-like syndrome with elevated fasting plasma glucose levels, elevated hepatic glucose output, and peripheral insulin resistance." (PMID 28442992, 2017). "One possible explanation for the discordance between INSR- and AKT2-associated human insulin resistance subphenotypes lies in the pronounced femorogluteal lipodystrophy associated with AKT2 mutation, albeit only in a single family to date, but not with INSR mutations." (PMID 27766312, 2016). "Insulin resistance (IR) in patients with metabolic syndrome (MetS), who are at high cardiovascular risk, is associated with impaired insulin signaling via the insulin receptor substrate-2- (Irs2-) AKT2 pathway in mononuclear leukocytes (MLs)." (PMID 22347652, 2011). "Therefore, our findings suggest that insulin resistance in the OLETF model is associated with decreased Akt2 expression and that acupuncture may relieve some of the insulin-resistance related symptoms by restoring Akt2 expression back to normal levels." (PMID 27738449, 2016). "Of the three known Akt isoforms (Akt1, Akt2, and Akt3) in insulin-sensitive tissues, defects in Akt2 and Akt3 particularly impair insulin-stimulated glucose transport in insulin resistance." (PMID 39125938, 2024). "There is evidence that AKT2 ablation in mice leads to hyperglycemia, hyperinsulinemia, insulin resistance, and diabetes development." (PMID 39201476, 2024). "For instance, it has been shown that liver-specific deletion of Akt1 and Akt2 led to glucose intolerance and insulin resistance." (PMID 39325536, 2024). "This is the first study to suggest that 17β‐estradiol replacement improves high‐fat diet‐induced insulin resistance, and this effect is accompanied by the alterations in the Akt2 and AS160 phosphorylation in insulin‐stimulated muscles of ovariectomized rats." (PMID 35238495, 2022). "A mouse study showed that BCAA inhibited Akt2 activation through mTORC1 and mTORC2 signals for a long time, resulting in liver metabolic disorder and severe liver insulin resistance." (PMID 36557202, 2022).
Insulin resistance (continued). "Our data suggest that E2 replacement improves HFD‐induced insulin resistance, and this effect is accompanied by the alterations in the Akt2 and AS160 phosphorylation in insulin‐stimulated muscles of OVX rats." (PMID 35238495, 2022). "Direct co-culture of SGBS with macrophages revealed that macrophages further promote adipose tissue inflammation and insulin resistance by inducing adipocyte apoptosis via blocking Akt2 signalling." (PMID 35986215, 2022). "The miR-146a is also related to insulin resistance as a modulator of the AKT2 gene that controls that resistance." (PMID 36143475, 2022). "They observed that the increased O-GlcNAc modification of IRS-1 and Akt2 reduced the insulin-stimulated phosphorylation of IRS-1 and Akt2, which induced insulin resistance characterized by prominently decreased GLUT4 translocation in adipocytes." (PMID 36005597, 2022). "We have previously reported insulin resistance dependent decrease in serine phosphorylation of Akt1, Akt2 and Akt3 in neuronal cells.We next proceeded to test the effect of PHLPP1 silencing on Akt isoforms in neuronal insulin signaling and resistance." (PMID 36376971, 2022). "The insulin-resistant rats showed significantly decreased (P<0.001) mean Akt2, IRS 1, and PI3K activities." (PMID 33953863, 2021). "In obesity and T2D, insulin resistance has been linked mainly to defects in the signalling pathway of phosphatidylinositol 3-kinase and protein kinase B (PI3K/Akt), particularly to the Akt2 isoform." (PMID 35002743, 2021). "Multiple studies have specified that Akt2 is responsible for insulin-dependent glucose uptake in humans as well as rodents, and its dysfunction is related to insulin resistance and impaired glucose tolerance, which goes hand in hand with our study." (PMID 34360895, 2021). "As Akt2 is an essential kinase in insulin resistance, we investigate the phosphorylation of Akt2 in CFTR–/– mice." (PMID 33659254, 2021). "Exhibited antioxidant effect, improved hepatic insulin resistance by modulating IRS1/PI3K/AKT2 pathways." (PMID 34299610, 2021). "Patients with a loss-of-function mutation of AKT2 suffered from the autosomal dominant inheritance of severe insulin resistance and diabetes mellitus, and AKT2 KO mice have been reported to exhibit hyperglycemia, hyperinsulinemia and glucose intolerance." (PMID 32252758, 2020). "In kidney diseases, trehalose has been found to ameliorate renal function in the polycystic kidney and Akt2 knockout-induced insulin resistance models." (PMID 32483422, 2020). "Insulin resistance occurs when obesity is accompanied by reduced gene expression of PI3K/AKT2/GLUT4 pathway." (PMID 32670384, 2020). "Mice with deletions in the PI3K catalytic subunit or AKT2 display insulin resistance and a type 2 diabetic phenotype." (PMID 32280711, 2020). "An interesting, recent finding revealed that P50T genetic variation in AKT2 gene, which leads to insulin resistance and hyperinsulinemia in the periphery, increased the glucose uptake in the brain as assessed by [18F]-FDG PET imaging." (PMID 31275108, 2019). "Knockout of AKT2 in a mouse model leads to a diabetes-like phenotype through peripheral insulin resistance and impaired glucose uptake into the cell, confirming a pivotal role of AKT2 in glucose homeostasis." (PMID 31752925, 2019). "On the one hand hyperinsulinemia compensating for insulin resistance promotes lipogenesis in the liver by both Akt2-dependent and Akt2-independent signaling events." (PMID 30250222, 2018). "Hepatic deletion of Akt1 and Akt2 isoforms resulted into glucose intolerance, insulin resistance and a defective insulin transcription in response to feeding." (PMID 30469501, 2018). "Insulin resistance due to insulin receptor (INSR) dysfunction is associated with none of these, but when due to dysfunction of the downstream kinase AKT2 phenocopies obesity-related insulin resistance." (PMID 27766312, 2016).